VAX2 (ventral anterior homeobox 2)
Description:
Transcription factor that may function in dorsoventral specification of the forebrain. Regulates the expression of Wnt signaling antagonists including the expression of a truncated TCF7L2 isoform that cannot bind CTNNB1 and acts therefore as a potent dominant-negative Wnt antagonist. Plays a crucial role in eye development and, in particular, in the specification of the ventral optic vesicle (By similarity). May be a regulator of axial polarization in the retina.
Synonyms: DRES93
Tractability: No criterion of Open Targets' tractability assessment is met for any kind of drug.
Gene: Protein-coding gene on chromosome 2 (70,900,576 to 70,965,373, forward strand). Ensembl gene ENSG00000116035.
Subcellular location: Nucleus
Subcellular location (Human Protein Atlas): Nuclear speckles
Gene Ontology:
Molecular function: protein binding; sequence-specific double-stranded DNA binding; DNA-binding transcription factor activity; DNA-binding transcription factor activity, RNA polymerase II-specific; RNA polymerase II cis-regulatory region sequence-specific DNA binding; chromatin DNA binding; DNA binding; DNA-binding transcription repressor activity, RNA polymerase II-specific; RNA polymerase II intronic transcription regulatory region sequence-specific DNA binding
Biological process: brain development; central nervous system development; ectoderm development; forebrain development; neuron differentiation; regulation of transcription by RNA polymerase II; visual perception; negative regulation of transcription by RNA polymerase II; regulation of DNA-templated transcription
Cellular component: chromatin; nucleus; cytoplasm
Genetic constraint (gnomAD): Loss-of-function variants: 10 observed, 11.17 expected, observed/expected ratio (o/e) 0.9, 90% interval 0.55 to 1.51. The upper end of that interval is the gene's LOEUF score, 1.51, which puts it in group 6 of 6, group 1 being the genes least tolerant of losing a copy. Missense variants: 476 observed, 369.21 expected, observed/expected ratio (o/e) 1.29, 90% interval 1.2 to 1.39. Synonymous variants: 183 observed, 168.6 expected, observed/expected ratio (o/e) 1.09, 90% interval 0.96 to 1.23.
Homologues: Orthologues: chimpanzee VAX2 (99% identical), macaque VAX2 (97% identical), guinea pig VAX2 (90% identical), pig VAX2 (88% identical), mouse Vax2 (88% identical), rat Vax2 (86% identical), dog VAX2 (67% identical), tropical clawed frog vax2 (61% identical), zebrafish vax2 (59% identical), Drosophila melanogaster E5 (18% identical), Caenorhabditis elegans ceh-2 (16% identical). Paralogues in human: VAX1 (50% identical), EMX1 (20% identical), EMX2 (19% identical).
Diseases named in the same sentence as VAX2 in open-access papers:
VAX2 is named in the same sentence as 22 diseases in open-access papers, as found by Europe PMC text mining. Sharing a sentence is not in itself a finding about the gene and the disease. The quoted sentences say what the papers report.
coloboma (7 papers, 2006 to 2020). An abnormality in which a part of a structure in one or both eyes is missing. "Nevertheless, the effect of loss of Vax2 expression in the ventral eye has already been carefully studied in Vax2 null mice and shown to cause profound defects in ventral eye formation and coloboma." (PMID 17173667, 2006). "Colobomas were rare and milder in Vax2 homozygous null mutants, but Vax1 and Vax2 double-mutant mice had severe colobomas that were fully penetrant." (PMID 32111086, 2020). "Injections of antisense morpholinos against Vax2 or Vax1 resulted in colobomas and reduced retinal pigment at the site of the choroid fissure in Danio rerio." (PMID 32111086, 2020). "Some of the Vax2-/- mice also display incomplete closure of the optic fissure and coloboma (with variable penetrance) and there is speculation in the literature that VAX2 might be responsible for a similar human phenotype." (PMID 26068435, 2015). "Both in this patient and in the Vax2-null mouse, the phenotype is mild compared to that associated both with a previously reported human VAX1 mutation and a targeted murine Vax1 deletion, where coloboma was fully penetrant and moderately severe." (PMID 26068435, 2015). "We found that depletion of kdm5c significantly downregulated vax1, vax2, pax6 expressions, while tbx5 expression was slightly reduced; thus, the reduced expression of DV-patterning markers may be responsible for the colobomas observed in kdm5c morphants." (PMID 30522514, 2018). "The patient did not manifest coloboma but this is not particularly surprising as in Vax2-/- mice this abnormality showed variable penetrance." (PMID 26068435, 2015). "Finally, increased Pax2 and Vax2 labeling at the site of the choroid fissure in the morphant-injected embryos compared to control-injected embryos suggests delayed closure of the optic fissure and may implicate these genes and/or the Pax2 pathway in the pathogenesis of the colobomas." (PMID 20485507, 2010).
gastric cancer (5 papers, 2023 to 2025). A primary or metastatic malignant neoplasm involving the stomach. "Functional studies have shown that high VAX2 expression significantly enhances the proliferation and invasion of gastric cancer cells." (PMID 40361105, 2025). "In contrast, in gastric cancer, VAX2 is upregulated and promotes proliferation and metastasis by repressing tumor suppressor genes." (PMID 40563675, 2025). "Interestingly, recent work in other cancers suggests an oncogenic role for VAX2, for example, VAX2 was found to be significantly upregulated in gastric cancer and to promote tumor cell proliferation and invasion." (PMID 41378293, 2025). "Similarly, VAX2 is significantly overexpressed in gastric cancer tissues and is correlated with advanced-stage disease and positive lymph node metastasis." (PMID 40361105, 2025). "High expression of VAX2 was found to accelerate the development of gastric cancer." (PMID 38801557, 2024).
bladder cancer (3 papers, 2019 to 2025). "Promoter hypermethylation of VAX2 has been associated with reduced gene expression and higher tumor grade in bladder cancer." (PMID 40563675, 2025). "They demonstrated that VAX2 and other genes hold significant potential as targets for novel therapeutic intervention, with traditional therapeutic options in the treatment of bladder cancer." (PMID 33817157, 2019). "The VAX2 has recently attracted many attentions in cancers and has been proved to regulate the malignant progression of thyroid cancer, breast cancer, and bladder cancer." (PMID 35432538, 2022).
distal renal tubular acidosis (3 papers, 2015 to 2023). A kidney disorder of impaired net acid secretion by the distal tubule characterized by hyperchloremic metabolic acidosis. "In addition, it is reported that VAX2 is involved in the pathological process of other diseases such as distal Renal Tubular Acidosis and high-grade non-muscle invasive bladder cancer." (PMID 33817157, 2019).
papillary thyroid carcinoma (3 papers, 2019 to 2025). "In contrast, in papillary thyroid carcinoma, elevated VAX2 expression is associated with poor prognosis, primarily due to the activation of the MEK/ERK signaling pathway, which promotes tumor cell proliferation, migration, and invasion." (PMID 40361105, 2025). "A previous report indicated that VAX2 is elevated in papillary thyroid carcinoma (PTC) samples in comparison to normal thyroid tissues, and reducing VAX2 expression significantly inhibits the malignant biological behaviors of PTC cells." (PMID 37865686, 2023).
glioma (2 papers, 2022 to 2025). A benign or malignant brain and spinal cord tumor that arises from glial cells (astrocytes, oligodendrocytes, ependymal cells). "In conclusion, FGFBP3, VAX2, and SHD were protective prognostic biomarkers against Macrophage M2 infiltration in low-grade glioma." (PMID 35432538, 2022).
glioblastoma (1 paper, 2025). The most malignant astrocytic tumor (WHO grade IV). "To investigate the biological relevance of candidate transcription factors enriched in the NSC-like compartment, we next performed functional validation of OTP, C1QL2, and VAX2 using the LN229 glioblastoma cell line (ATCC, CRL-2611)." (PMID 41378293, 2025). "VAX2 is a homeobox gene involved in neural development, and it has not been widely studied in glioblastoma." (PMID 41378293, 2025).
lymph node metastasis (1 paper, 2023). "The findings showed that increased VAX2 expression was significantly associated with differentiation (P = 0.03), AJCC T stage (T1/2 vs. T3/4, P = 0.013, Fig. 1E1), TNM stage (I/II vs. III/IV, P = 0.001, Fig. 1E2), and lymph node metastasis (P = 0.001, Fig. 1E3, N0 vs. N1-3)." (PMID 37865686, 2023).
optic atrophy (1 paper, 2015). A disorder characterized by loss of optic nerve fibers. "Additionally, there was optic atrophy similar to Vax2-/- mice which may be primary or secondary to the retinal dystrophy." (PMID 26068435, 2015).
cancer (10 papers, 2015 to 2025). A tumor composed of atypical neoplastic, often pleomorphic cells that invade other tissues. "VAX2 is a transcription factor linked to cancer progression and dysregulation." (PMID 40563675, 2025). "Research on VAX2 in cancer is relatively limited, and its role seems to vary across different malignancies." (PMID 40361105, 2025). "Semi-quantitative scoring showed that the expression of the VAX2 protein in cancer tissues was significantly higher than that in their counterpart tissues." (PMID 37865686, 2023). "Thus, VAX2 may be associated with different forms of cancer, including GC." (PMID 37865686, 2023). "Ventral anterior homeobox 2 (VAX2) gene is a key regulating factor for the development of the ventral region of the eye, and has recently attracted much attention from the cancer treatment field." (PMID 33817157, 2019).
tumor (4 papers, 2023 to 2025). "Univariate Cox regression analysis revealed a hazard ratio of 2.30 for OS, while multivariate Cox regression analysis, adjusted for age, tumor stage, and grade, confirmed VAX2 as an independent risk factor for OS, with a hazard ratio of 2.14." (PMID 40361105, 2025). "Additional experiments demonstrated that VAX2 knockdown markedly inhibited tumor growth in E0771 and 4T1 cell-derived xenograft models and substantially reduced tumor burden in C57BL/6 and BALB/c mice." (PMID 40361105, 2025). "The intersection of these two gene sets yielded 27 genes regulated by VAX2 and highly expressed specifically in tumor cells, forming the VAX2 signature (VAX2.Sig)." (PMID 40361105, 2025). "To further investigate the role of VAX2 in tumor malignancy, we conducted both in vitro and in vivo experiments." (PMID 40361105, 2025). "Multiplex immunofluorescence analysis of E0771 mouse tumor tissues showed that VAX2 knockdown significantly decreased the number of mCAFs within the tumor microenvironment." (PMID 40361105, 2025). "Tumor cases usually displayed VAX2-positive staining, while adjacent normal cases were either VAX2-negative or weakly VAX2-positive." (PMID 37865686, 2023). "In vitro, ablation of SE269 or knockdown of VAX2 in MDA468 and CAL51 cells significantly suppressed tumor cell proliferation, invasion, and migration." (PMID 40361105, 2025). "In human xenograft models in vivo, VAX2 overexpression in MDA231 cells accelerated tumor growth and increased tumor burden in BALB/c nude mice." (PMID 40361105, 2025). "Further in vitro and in vivo studies demonstrated VAX2’s critical role in regulating the mesenchymal development subtype of TNBC and driving tumor progression." (PMID 40361105, 2025). "We found that VAX2 drived the expression of characteristics of this subtype, activated ECM-related pathways, and directly promoted tumor cell proliferation, invasion, and migration." (PMID 40361105, 2025). "For example, in high-grade non-muscle-invasive bladder cancer, VAX2 functions as a tumor suppressor, as evidenced by increased methylation and decreased expression in high-grade tumors." (PMID 40361105, 2025). "However, VAX2 is not correlated with extra clinical features, including age (P = 0.934), gender (P = 0.465), and tumor size (<10 cm3 vs. ≥10 cm3, P = 0.584) in GC." (PMID 37865686, 2023).
infection (1 paper, 2022). The state of being infected such as from the introduction of a foreign agent such as serum, vaccine, antigenic substance or organism. "Potency against WT was considerably improved after Delta breakthrough infection compared to the second vaccine dose (Vax2; IC50 = 182 ng/ml vs. IC50 = 50 ng/ml, P = 0.0013) but not compared to the third vaccine dose (IC50 = 98 ng/ml, P = 0.62)." (PMID 36149398, 2022). "The number of WT RBD-specific MBCs after Delta breakthrough infection was significantly higher than after the second or third vaccine dose (Delta vs. Vax2, P < 0.0001, and Delta vs. Vax3, P = 0.011)." (PMID 36149398, 2022). "Compared to individuals who received two mRNA vaccine doses, Delta breakthrough infection resulted in 11-fold increased geometric mean half-maximal neutralizing titer (NT50; P = 0.0003, Vax2 vs. Delta)." (PMID 36149398, 2022).
VAX2 also shares sentences with these, for which no sentence is quoted: breast cancer (2 papers); glaucoma (1); lymphoma (1); microphthalmia (1); neuroblastoma (1); renal cell carcinoma (1); Retinal dystrophy (1); rheumatoid arthritis (1); sitosterolemia (1); thyroid cancer (1).